MYB (MYB proto-oncogene, transcription factor)
Diseases named in the same sentence as MYB in open-access papers (continued):
Sharing a sentence is not in itself a finding about the gene and the disease.
breast carcinoma (continued). "STAT1-/- ERα+ mammary tumors also showed elevated transcription of genes characteristic of luminal breast cancers (for example, keratin 8, keratin 18, XBP1, GATA3, MYB, AREG, and FOXA1)." (PMID 22264274, 2012). "The studies reported here have shown that MYB has an important role in the control of MEC differentiation and in the resistance of mammary carcinoma cells to apoptosis." (PMID 20659323, 2010). "MYB expression is directly and positively regulated by estrogen/ER signaling in MCF-7 and other ER positive breast cancer cells." (PMID 20659323, 2010). "ER+ breast cancer cell lines were shown to be dependent on MYB expression, while ER− breast cancer cell lines were not." (PMID 40190354, 2025). "The MYB protein is a critical therapeutic target for various cancer types, such as T cell acute lymphoblastic leukemia (T-ALL), breast cancer, and prostate cancer." (PMID 40234694, 2025). "Notably, the hormone estradiol drives ER-positive breast cancers, but its anticancer effects on CRC upon MYB suppression deserve more investigation." (PMID 38835346, 2024). "In ER+ breast cancer cell lines, CDK9 targeting has been shown to reduce the level of MYC and MYB expression and E2-independent tumor cell proliferation but little information is available of the effectiveness of CDK9 inhibition in reducing tumor growth in vivo." (PMID 37801608, 2024). "Conversely, MYB could also activate miR-200, whereas ZEB1 could directly suppress MYB expression in breast cancer cells, which suggests a context-dependent role of MYC in certain cancers." (PMID 38835346, 2024). "A negative correlation between MYB and miR-143-3p expression was found in breast cancer tissues and cells." (PMID 34876130, 2021). "Finally, using miR mimic overexpression and TIMP2 siRNA knockdown, we show that a miR-221/222, miR-503 → MYB, MYBL1 → TIMP2 axis stimulates migration and invasion of MCF-7 breast cancer cells." (PMID 30833639, 2019). "Similar to MYB, both MYBL1 and MYBL2 are upregulated by ESR1 signaling in breast cancer cells." (PMID 30833639, 2019). "Finally, MYB, MYBL1 and MYBL2 were reported to be upregulated by ESR1 signaling in breast cancer cells." (PMID 30833639, 2019). "Additionally, TiHo-0906 cells at low and high passage also displayed CNGs in regions harbouring other known breast cancer-related genes like FOXO3 and MYB (FCA B2), AKT1 (FCA B3), and GATA-3, CCND2, CDK4 and PFDN5 (FCA B4)." (PMID 30185896, 2018). "Here, we have explored this possibility and found that CDK9i down-regulate MYB expression and selectively induce apoptosis in ER+ve/MYB+ve but not ER−ve/MYB−ve breast cancer cells." (PMID 26812885, 2016). "The anti-apoptotic role of MYB in breast cancer was not immediately apparent since shRNA-mediated knockdown did not induce significant apoptosis by itself." (PMID 26812885, 2016). "Taken together these data suggest that MYB regulation of BCL2 underlies the heightened sensitivity of ER+ve compared to ER−ve breast cancer cells to CDK9 inhibition, and that these compounds represent a potential therapeutic for ER+ve breast cancers and possibly other MYB-dependent cancers." (PMID 26812885, 2016). "Indeed, we observed an inverse relation between MYB and ZEB1 expression in two in vitro EMT cell models, in matched human breast tumors and lymph node metastases, and in human breast cancer cell lines." (PMID 24283570, 2013). "For example, MYB and NDRG1 are related to ER+ breast cancer and TNBC, respectively." (PMID 22343619, 2012). "However, MYB knockdown greatly enhanced the sensitivity of breast cancer cells to several chemical agents, an effect mediated (at least in part) by the MYB target gene BCL2, since knockdown of the latter mimicked the sensitisation effects of MYB knockdown." (PMID 26812885, 2016).
breast carcinoma (continued). "This work identifies ZEB1 as a transcriptional repressor of MYB and suggests a reciprocal MYB-ZEB1 repressive relation, providing a mechanism through which proliferation and the epithelial phenotype may be coordinately modulated in breast cancer cells." (PMID 24283570, 2013). "One might suspect that the G1 phase growth arrest that accompanies MYB knockdown and differentiation in mammary carcinoma cells may be important but is unlikely to be sufficient, because only limited differentiation was observed following MYB knockdown alone." (PMID 20659323, 2010). "Importantly, we have also recently shown that MYB is required for the proliferation of ER positive, but not ER negative, breast cancer cell lines, identifying for the first time a functional role for MYB in breast cancer." (PMID 20659323, 2010). "The miR-221/222/503 – MYB/MYBL1 - TIMP2 – cell motility axis was recapitulated in both T47D cells (Luminal A subtype) and SKBr-3 cells (HER2-positive subtype), suggesting a the signaling axis is universal rather than cell line/breast cancer subtype specific." (PMID 30833639, 2019).
adenoid cystic carcinoma (72 papers, 2010 to 2026). A malignant tumor arising from the epithelial cells. "Samples from the ACC class shared the molecular profile (DNA methylation, MYB rearrangement, recurrent loss of chromosome 6q38) of adenoid cystic carcinomas and most likely represent high-grade adenoid cystic carcinomas." (PMID 36443295, 2022). "Adenoid cystic carcinoma (AdCC) of the breast is a rare indolent carcinoma of salivary gland-type tumors, frequently associated with MYB genetic alteration." (PMID 35590093, 2022). "Moreover, Stenman and co-workers reported that a MYB-NFIB fusion is a hallmark of adenoid cystic carcinomas (ACC) of the breast, head and neck, and that deregulation of the expression of MYB is a key oncogenic event in the pathogenesis of ACC." (PMID 21338522, 2011). "Molecular characterization plays a growing role in diagnosis and precision therapy, exemplified by the identification of ETV6–NTRK3 fusions in secretory carcinoma and MYB rearrangements in adenoid cystic carcinoma." (PMID 41301002, 2025). "For adenoid cystic carcinoma, multiple retrospective institutional series comprising aggregate numbers exceeding 200 cases, combined with well-characterized MYB/MYBL1 rearrangements and long-term outcome data, provide a robust evidence base." (PMID 41301002, 2025). "MYB expression has been seen in basal cell adenoma, basal cell adenocarcinoma, and adenoid cystic carcinoma." (PMID 39221392, 2024). "MYB is a transcription factor altered in adenoid cystic carcinoma (ACC), a deadly cancer originating in exocrine glands." (PMID 38112379, 2024). "Patients with adenoid cystic carcinoma and MYB overexpression are included in the ongoing MYPHISMO trial with novel vaccination approach, used synergistically with programmed cell death protein 1 (PD-1) inhibitors." (PMID 37439929, 2023). "83% of a rare type of TNBS (adenoid cystic carcinomas (ACC) of the breast) carry the MYB-NFIB fusion." (PMID 37744342, 2023). "Previously reported gene translocations and fusion oncogenes include the CRTC1/3-MAML2 fusion gene in mucoepidermoid carcinoma and the MYB-NFIB fusion gene in adenoid cystic carcinoma." (PMID 36431032, 2022). "Fusions between MYB, MYBL1 and NF1B genes are associated with adenoid cystic carcinoma and are preserved in metastases." (PMID 35397067, 2022). "MYB translocations are also reported in 60–80% of adenoid cystic carcinomas, mainly with the MYB::NFIB fusion transcript, and in pediatric gliomas." (PMID 36077669, 2022). "NOTCH1 and truncated MYB—which together define a common subtype of adenoid cystic carcinoma —were also selected for the fly model, bringing the final number of modeled cancer drivers to six patient variants modeled by five targeted fly genes." (PMID 33733072, 2021). "For example, JQ1, a BET inhibitor, broke up super-enhancers by inhibiting BRD4 and deregulating MYB transcription, consequently inhibiting adenoid cystic carcinoma growth." (PMID 34054916, 2021). "As adenoid-cystic carcinomas can feature genetic alterations in the MYB and MYBL1 genes, in addition to typical perineural invasion, further molecular pathological analyses of the tissue were performed." (PMID 32443830, 2020). "Several chromosomal fusions, such as the MYB-NFIB fusion in adenoid cystic carcinoma, show dependence on IGF1R signaling, and IGF1R shows promise as a clinical target." (PMID 31980503, 2020). "Using dual-color FISH, we analyzed 21 cases, including 13 cylindromas, 7 spiradenomas, and 1 cylindroma–spiradenoma hybrid tumor in addition to an adenoid cystic carcinoma case known to carry the MYB-NFIB fusion as a control." (PMID 31101826, 2019). "Despite the small size of our study, we believe the NanoString assay described provides researchers a promising tool for the accurate detection and quantification of MYB fusions in patients with adenoid cystic carcinoma." (PMID 31301736, 2019).
adenoid cystic carcinoma (continued). "Myeloblastosis viral oncogene homolog-like 1 (MYBL1) belongs to the proto-oncogene family, and this MYB gene has been reported as an oncogene of adenoid cystic carcinoma." (PMID 31505835, 2019). "FISH was particularly helpful for diagnosing malignant tumours (mucoepidermoid carcinoma with a MECT1-MAML2 fusion, adenoid cystic carcinoma with a MYB translocation and secretory carcinoma with an ETV6 translocation)." (PMID 31805712, 2019). "Recurrent gene fusions were primarily identified in prostate cancer (TMPRSS2::ERG) and adenoid cystic carcinoma (MYB::NFIB) in 1.74% (9/517) and 1.35% (7/517), respectively in the overall cohort." (PMID 31491926, 2019). "A previous report has suggested a role for MYB-NFIB fusions in the pathogenesis of both adenoid cystic carcinoma and cylindroma." (PMID 31101826, 2019). "In the present pilot study, we investigated the feasibility of employing NanoString technology to detect MYB-NFIB fusion transcripts in archival FFPE adenoid cystic carcinoma tissues." (PMID 31301736, 2019). "An interesting feedback loop exists in adenoid cystic carcinoma in which MYB protein-bound enhancers can interact long range to activate the promoter of MYB, and ACCMYB-TGFBR3 translocation also places the super-enhancer in contact with the promoter of MYB." (PMID 29149895, 2017). "Finally, adenoid cystic carcinoma, a biphasic cell tumour with frequent rearrangement of the MYB or MYBL1 gene, is an important differential diagnosis of MSA." (PMID 38982505, 2024). "These include fusions of the ETV6 gene in secretory carcinoma (SC), MYB/MYBL1::NFIB in adenoid cystic carcinoma (AdCC), CRTC1/CRTC3::MAML2 in mucoepidermoid carcinoma (MEC), and EWSR1::ATF1 in hyalinizing clear cell carcinoma as the most frequent and best characterized gene fusions." (PMID 38217715, 2024). "Furthermore, the MYB gene is moved closer to a distal SE via a chromosomal rearrangement, resulting in increased MYB expression in adenoid cystic cancer (ACC)." (PMID 37501079, 2023). "In fact, demonstrating a rearrangement of MYB, MYBL1, PLAG1, HMGA2, NTRK3, and a BRAF mutation in the appropriate morphological context is diagnostic of adenoid cystic carcinoma, cutaneous mixed tumor, secretory carcinoma, syringocystadenoma papilliferum, and tubular adenoma." (PMID 35158743, 2022). "Even in the UK, routine testing for MAML2 rearrangement in mucoepidermoid carcinoma has been the norm only since 2015–2016 with FISH the most widely available test, whereas MYB testing in adenoid cystic carcinoma is still only available in a handful of specialist centres." (PMID 35622296, 2022). "Finally, recurrent translocations resulting in MYB-NFIB gene fusions have been identified as key drivers of adenoid cystic carcinoma (ACC), a slow-growing aggressive cancer often arising in the salivary glands." (PMID 35406726, 2022). "Furthermore, FISH revealed MYB breaks prototypical for adenoid cystic carcinomas in three specimens with SNUC morphology." (PMID 36443295, 2022). "The MYB-NF1B gene fusion upregulates MYB and appears to be specific to adenoid cystic carcinoma." (PMID 35397067, 2022). "MYB has also been implicated in certain non-hematopoietic tumors, such as breast and colon cancer, adenoid cystic carcinoma (ACC), and diffuse low-grade pediatric gliomas." (PMID 35008207, 2021). "contended that MYB-NFIB gene fusion promoted the aggressive behavior in adenoid cystic carcinoma." (PMID 34211850, 2021). "Genetically, MYB-NFIB fusion gene is a prevalent feature of adenoid cystic carcinoma." (PMID 32487046, 2020). "For example, the MYB–NFIB fusion in adenoid cystic carcinoma is regulated by IGF1R through an autocrine loop, and IGF1R is a downstream target of the EWSR1–WT1 and PAX3–FKHR fusions in desmoplastic small round cell tumors and alveolar rhabdomyosarcoma, respectively." (PMID 31426421, 2019). "MYBL1 is a driver of adenoid cystic carcinoma when related to MYB." (PMID 29697361, 2018).
adenoid cystic carcinoma (continued). "Although the exact role(s) of MSANTD3 in AcCC oncogenesis remain to be determined, it is also intriguing that MYB itself, which of course also harbors a Myb/SANT-like domain, is part of a gene fusion that characterizes a different salivary gland tumor: MYB-NFIB in adenoid cystic carcinoma." (PMID 28212443, 2017). "MYB activation is proposed to underlie development of adenoid cystic cancer (ACC), an aggressive salivary gland tumor with no effective systemic treatments." (PMID 25587024, 2014). "Similarly, chromosomal translocations juxtaposing SE to the MYB locus were reported in adenoid cystic carcinoma, with 3-C (chromosome conformation capture) data supporting a direct interaction between translocated SE and MYB promoter, allowing an increased transcription of this oncogenic TF." (PMID 35053311, 2022). "However, unlike fusion transcripts that occur in other salivary gland tumors, which result in the production of fusion proteins like the MYB-NFIB fusion genes produced in adenoid cystic carcinoma, in this case the result is a more highly transcribed NR4A3 or NR4A2 gene, but no fusion proteins." (PMID 32867110, 2020). "The two Adenoid cystic carcinomas both fell into IntClust 4, consistent with their known indolent behaviour despite their basal-like features, and have recently been shown to harbour a characteristic MYB-NFIB gene translocation with low background genetic instability." (PMID 29532008, 2018). "In the last decade, advances in molecular techniques have demonstrated recurrent genetic alterations in some salivary gland tumors, including the fusion of genes such as ETV6 in secretory carcinoma, MYB and MYBL1 in adenoid cystic carcinoma, and MAML2 in MEC." (PMID 39958930, 2025). "The significant upregulation of MYB in TNBC cells suggests its potential as a therapeutic target, consistent with observations in adenoid cystic carcinoma (ACC), where MYB inhibition via peptidomimetics suppresses tumor growth." (PMID 41141380, 2025). "Recurrent translocations between MYB and NFIB occur in a high percentage of cases of adenoid cystic carcinoma (ACC), resulting in the expression of oncogenic MYB/NFIB fusion proteins." (PMID 38542205, 2024). "Fusions among specific genes, namely myeloblastosis (MYB), MYB proto-oncogene like 1 (MYBL1), and nuclear factor I B (NFIB), have been related to adenoid cystic carcinoma." (PMID 37970205, 2023). "Recent studies have disclosed transcription factor MYB as a potential drug target for malignancies that are dependent on deregulated MYB function, including acute myeloid leukemia (AML) and adenoid cystic carcinoma (ACC)." (PMID 35406726, 2022). "Evidence in adenoid cystic carcinoma with low TMB and lower immune infiltration demonstrated that recurrent MYB-NFIB fusions also exhibit immunogenic peptides in approximately 60% of patients." (PMID 34867976, 2021). "Around 80–90% of adenoid cystic carcinomas (AdCC) reveal MYB or MYBL1 activation by gene fusion, leading to overexpression of MYB-NFIB or MYBL1-NFIB fusion protein, respectively." (PMID 33237469, 2021). "Studies of the role of MYB in human malignancies have highlighted MYB as a potential drug target for acute myeloid leukemia (AML) and adenoid cystic carcinoma (ACC)." (PMID 35008207, 2021). "Adenoid cystic carcinoma (ACC) is a slow growing salivary gland malignancy that is molecularly characterized by t(6:9)(q22–23;p23–24) translocations which predominantly result in MYB-NFIB gene fusions in nearly half of tumours." (PMID 31301736, 2019). "In our current study we sought to determine if MYB and MYB-NFIB transcript expression in archival FFPE head and neck adenoid cystic carcinomas could be detected using NanoString probe based methodology." (PMID 31301736, 2019). "MYB-NFIB and MYBL1-NFIB gene fusions frequently occur in adenoid cystic carcinoma." (PMID 27083054, 2016).
adenoid cystic carcinoma (continued). "Furthermore, MYB is considered a potential target for anticancer therapy for acute myeloid leukemia (AML), T-cell acute leukemia (T-ALL), adenoid cystic carcinoma (ACC), and other types of cancer, and also for other diseases like inflammatory osteoclast formation and bone resorption." (PMID 39844998, 2025). "Thus, regardless of scoring criteria, MYB protein has limited utility in separating adenoid cystic carcinoma from HMSC." (PMID 39319059, 2024). "Finally, the existence of a ceruminous pleomorphic adenoma was assumed due to a lack of nuclear pleomorphism, no increased mitotic rate, no perineural invasion and no fusion transcripts of the MYB or MYBL1 gene loci for an adenoid cystic carcinoma." (PMID 32443830, 2020). "Due to the absence of nuclear pleomorphism, no increased mitotic rate, no perineural invasion and no fusion transcripts of the MYB or MYBL1 gene loci, an adenoid cystic carcinoma could be excluded." (PMID 32443830, 2020). "An obvious differential diagnosis to HMSC is adenoid cystic carcinoma (ACC), which could be ruled out in the majority of cases, e.g., by the presence of a dysplastic epithelium, “squamous differentiation”, absence of Pn and absence of MYB gene fusions (data not shown)." (PMID 34578442, 2021).